CRIP3 (cysteine rich protein 3)
Synonyms: CRP-3; h6LIMo; TLP-A; bA480N24.2; TLP
Tractability: PROTAC: its protein half-life has been measured.
Safety:
Unwanted effects reported when the protein is acted on. In parentheses: how it was acted on, where the effect was seen, and who reports it.
diarrhea (source: ClinPGx)
drug toxicity (source: ClinPGx)
Gene: Protein-coding gene on chromosome 6 (43,299,710 to 43,308,874, reverse strand). Ensembl gene ENSG00000146215.
Subcellular location: Cytoplasm
Subcellular location (Human Protein Atlas): Nuclear speckles
Gene Ontology:
Cellular component: cytoplasm
Genetic constraint (gnomAD): Loss-of-function variants: 23 observed, 31.47 expected, observed/expected ratio (o/e) 0.73, 90% interval 0.52 to 1.04. The upper end of that interval is the gene's LOEUF score, 1.04, which puts it in group 4 of 6, group 1 being the genes least tolerant of losing a copy. Missense variants: 259 observed, 258.46 expected, observed/expected ratio (o/e) 1, 90% interval 0.9 to 1.11. Synonymous variants: 89 observed, 95.25 expected, observed/expected ratio (o/e) 0.93, 90% interval 0.79 to 1.11.
Homologues: Orthologues: chimpanzee CRIP3 (99% identical), macaque CRIP3 (98% identical), guinea pig CRIP3 (89% identical), dog CRIP3 (88% identical), mouse Crip3 (88% identical), rabbit CRIP3 (88% identical), pig CRIP3 (83% identical), rat Crip3 (81% identical), zebrafish crip3 (71% identical), tropical clawed frog crip3 (70% identical). Paralogues in human: CRIP2 (62% identical), ZFHX3 (25% identical), ZFHX4 (24% identical), ZFHX2 (22% identical), LHX9 (22% identical), CRIP1 (21% identical), LHX2 (21% identical), LMX1B (20% identical), LHX1 (20% identical), LHX5 (20% identical), LHX3 (19% identical), LHX4 (19% identical), and 8 more.
Diseases named in the same sentence as CRIP3 in open-access papers:
CRIP3 is named in the same sentence as 12 diseases in open-access papers, as found by Europe PMC text mining. Sharing a sentence is not in itself a finding about the gene and the disease. The quoted sentences say what the papers report.
hearing loss (2 papers, 2020 to 2023). "Variants on the genes CRIP3, which plays a role in T-cell proliferation and metal-ion binding, and SLC22A7, have been found to be associated with hearing loss in humans." (PMID 38098998, 2023).
cardiac hypertrophy (1 paper, 2023). "Candidate gene identification analyses of exercise-induced cardiac hypertrophy identified five potential regulatory transcripts: IL31ra, Fam167b, Tafa5, Crip3, and Nanos1 (p < 0.01)." (PMID 37178122, 2023).
head and neck squamous cell carcinoma (1 paper, 2025). A squamous cell carcinoma that arises from any of the following anatomic sites: lip and oral cavity, nasal cavity, paranasal sinuses, pharynx, larynx, and salivary glands. "Studies have shown that CRIP3 is also closely related to tumorigenesis and can be used as a biomarker of epithelial tumors such as head and neck squamous cell carcinoma, lung squamous cell carcinoma, and prostate cancer, and constructed models can effectively predict the prognosis." (PMID 40118853, 2025). "CRIP3 was identified as a novel prognostic biomarker in cancers such as head and neck squamous cell carcinoma, lung squamous cell carcinoma, and prostate cancer, among which the CRIP3 hypomethylated epigenotype in lung squamous cell carcinoma was significantly associated with poor prognosis." (PMID 40118853, 2025).
prostate carcinoma (1 paper, 2025). A carcinoma that arises from epithelial cells of the prostate gland. "The methylation status of CRIP3 in prostate biopsy and urine is an important marker for postoperative recurrence and prognosis of patients with prostate cancer." (PMID 40118853, 2025).
Zinc deficiency (1 paper, 2021). A deficiency of the essential metal Zinc; an essential cofactor for many enzymes. "Since zinc deficiency is known to be a cause of OS, we speculate that the downregulation of CRIP1 and CRIP3 is affected by OS-induced pathways that contribute to the reduced availability of zinc in cells." (PMID 34944646, 2021).
cancer (4 papers, 2020 to 2025). A tumor composed of atypical neoplastic, often pleomorphic cells that invade other tissues. "One recent report identified a 3-marker urine-based panel assay consisting of miR-24, miR-30c and CRIP3 methylation which exhibited a high NPV of 91% for reclassifying low-grade into high-grade cancers in a retrospective cohort of 103 PC patients on AS." (PMID 35406500, 2022).
CRIP3 also shares sentences with these, for which no sentence is quoted: infection (5 papers); atherosclerosis (1); cardiomyopathy (1); lung squamous cell carcinoma (1); Parkinson disease (1); Tinnitus (1).